REN (renin)
Diseases named in the same sentence as REN in open-access papers (continued):
Sharing a sentence is not in itself a finding about the gene and the disease.
Hypertension (continued). "Therefore, ACE (EC 3.4.15.1) and/or renin inhibition help to manage hypertension and offer cardiovascular protection by limiting the physiological level of angiotensin II." (PMID 32610462, 2020). "Although the etiology of essential hypertension is unknown, serum uric acid (SUA), the final product of the purine metabolism, has been hypothesized to activate intrarenal renin-angiotensin system (RAS), which can cause injury to pre-renal blood vessels." (PMID 33072398, 2020). "Additionally, it has been reported that people with low-renin essential hypertension have increased extracellular and plasma fluid volumes." (PMID 32992705, 2020). "Indeed, the mechanisms of pressure natriuresis are substantially impaired as age increases, along with an increased prevalence of the salt-sensitive pattern and the frequency of low-renin essential hypertension." (PMID 32645850, 2020). "Furthermore, with high blood pressure, overactivation of the renin–angiotensin system is considered to contribute to AD pathogenesis." (PMID 31906539, 2020). "Overweight or obesity could activate the sympathetic nervous and renin-angiotensin systems as well as increase the reabsorption of kidneys via sodium retention, leading to the development of obesity-related high blood pressure." (PMID 33005450, 2020). "IR may be responsible for high blood pressure via direct stimulation of renin–angiotensin–aldosterone system, activation of sympathetic system and downregulation of the natriuretic peptide system." (PMID 32850773, 2020). "Third, while our trial demonstrated transient changes in the renin-angiotensin-aldosterone levels and renal function, questions remain about the value of pool walking in protecting against hypertensive disorders in pregnancy in the long-term and dose-response effects." (PMID 32076019, 2020). "However, recently, the use of partial renin peptides has been examined for the development of a safe and effective hypertension vaccine." (PMID 31485348, 2019). "The renin–angiotensin system (RAS) is best known as a hormonal system with a physiological role in the maintenance of circulatory and fluid homeostasis, i.e., a classical hormonal system associated with human hypertension and diabetes." (PMID 31284538, 2019). "Renin-angiotensin system inhibition is a target for hypertension control." (PMID 31596365, 2019). "In the context of ANP amount and renin activity, sugared omija might act as a potential treatment measure for hypertension patients and may be better than raw omija." (PMID 31480566, 2019). "With the elucidation of licorice constituents and the discovery that 3MGA and GA affect the renin-angiotensin-aldosterone-system, pseudohyperaldosteronism is the obvious adverse effect; however, other side effects such as hypertension, hypokalemia and hypernatremia have also been proven." (PMID 31615045, 2019). "The mechanisms of increased RSNA in the pathogenesis of hypertension include increased tubular sodium reabsorption and water retention, decreased renal blood flow and glomerular filtration rate, and increased renin secretion from the juxtaglomerular cells which activates RAS." (PMID 30866441, 2019). "The probable pathophysiological mechanism of hypertension in our case could be the tumour compressing the renal artery and activating the renin-angiotensin axis." (PMID 31632881, 2019). "Additionally, NAFLD is known to induce dysregulation of the renin-angiotensin-aldosterone system in animal models, leading to arterial hypertension." (PMID 31682638, 2019). "In obese subjects, several mechanisms may lead to hypertension such as insulin and leptin resistance, perivascular adipose tissue dysfunction, renal impairment, renin-angiotensin-aldosterone-system activation and sympathetic nervous system activity." (PMID 31330870, 2019).
Hypertension (continued). "Thus, a typical biochemical profile in an African American person with hypertension is a low or high plasma aldosterone concentration, a low or suppressed plasma renin activity or direct renin concentration, and suppressed angiotensin I and II." (PMID 30832344, 2019). "Renin is expressed in the CD and is upregulated in Ang II-dependent hypertension." (PMID 31680980, 2019). "The renin-angiotensin system (RAS) is deeply involved in not only hypertension but also lifestyle-related diseases, and may contribute to the pathological mechanism in dementia; thus, RAS regulation is expected to prevent dementia." (PMID 31867123, 2019). "1,25 dihydroxy vitamin D (1,25(OH)2D) has been shown to regulate the major blood pressure regulating hormone, renin, in the kidneys, and thus acting as an inhibitor of the renin-angiotensin system, which is beneficial since an over-activation of the renin-angiotensin system can lead to hypertension." (PMID 30641861, 2019). "Since the Cx40−/− and Cx40−/−Panx1−/− mice exhibit cardiac hypertrophy, hypertension, and renin dysregulation, reductions in lifespan may become more apparent in an aged cohort of mice; however, this remains to be investigated." (PMID 30745457, 2019). "In addition, obesity can also activate renin-angiotensin-aldosterone system (RAAS), which is an important cause of hypertension." (PMID 31794594, 2019). "They suggest this leads to excessive release of placental renin and Ang peptides into the mother creating a situation that is analogous to the effects of Ang II-dependent hypertension or two kidney one clip (2K-1C) hypertension." (PMID 31551925, 2019). "Therefore, the renin-angiotensin system and sympathetic nervous system create a positive feedback loop to increase hypertension in obese individuals." (PMID 31214598, 2019). "In patients with hypertension, an elevated aldosterone–renin ratio (ARR) is used as a screening parameter, followed by confirmatory testing (salt loading, fludrocortisone or captopril administration, which all fail to sufficiently lower aldosterone levels in PA)." (PMID 31695023, 2019). "Since renin enzymatic activity is species-specific, a transgenic model of hypertension due to insertion of the human angiotensinogen (AGT) gene in Sprague Dawley rats allowed for characterizing the contribution of a non-renin dependent mechanism for Ang II actions in their blood and heart tissue." (PMID 31803758, 2019). "Therefore, prompted by the successful development of vaccines for infectious diseases, active and passive immunotherapies targeting renin were examined as early approaches for the treatment of hypertension." (PMID 31485348, 2019). "It has also been further reported that vitamin D is a negative regulator of the RAS and relevant to the regulation of hypertension and cardiovascular disease through downregulation of renin secretion; in addition, RAS activity is increased markedly in VDR-null mice." (PMID 31284538, 2019). "The renin-angiotensin-aldosterone-system (RAAS) is one important hormonal axis in hypertension." (PMID 31052201, 2019). "Activation of the sympathetic nervous system, the amount of intra-abdominal and intra-vascular fat, sodium retention leading to increase in renal reabsorption, and the renin-angiotensin system are considered to have important functions in the pathogenesis of obesity related hypertension." (PMID 31117945, 2019). "Site-specific pharmacological inhibition of COX-2 in the CD may help to prevent tubular damage during states of activation of intratubular renin–angiotensin system, such as hypertension and diabetes." (PMID 31396082, 2019). "In addition, the inflammasome appears to contribute to the development of hypertension in renin-dependent and independent hypertension under the effect of salt, angiotensin II but also the sympathetic nervous system and endothelin." (PMID 31608291, 2019).
Hypertension (continued). "For example, the renin-angiotensin system (RAS) represents a critical modulator of blood pressure homeostasis, the dysfunction of which is a common cause of the development of hypertension." (PMID 30906260, 2019). "Additionally, in animal models of diabetes and hypertension, the synthesis and secretion of prorenin and renin are greatly augmented in the principal cells of the CD, supporting the concept of a local activation of a tubular renin–angiotensin system." (PMID 31396082, 2019). "The central pathomechanism that underlies hyponatremic hypertension syndrome (HHS) is the stimulation and activation of the renin-angiotensin-aldosterone (RAA) axis which consequently trigger hypertension through vasoconstriction as well as fluid and salt retention." (PMID 30791890, 2019). "In the current study we therefore aimed to investigate whether Aliskiren, a renin-inhibitor used to treat arterial hypertension, may improve outcome in a mouse model of ischemic stroke when applied centrally and in a dose not affecting blood pressure." (PMID 31551909, 2019). "Therefore, FGF23 is thought to contribute to the development of hypertension by modulating the renin–angiotensin–aldosterone system (RAAS)." (PMID 31698866, 2019). "Placental stress and alterations in methylation of promoter regions of renin-angiotensin system (RAS)-related elements could be involved in UFP exposure-related programming of hypertension." (PMID 30691489, 2019). "Moreover, augmented mineralocorticoid activity is increasingly documented in patients with resistant hypertension and so-called low-renin hypertension, considering the efficiency of mineralocorticoid receptor (MR) blockade in these patients." (PMID 31191352, 2019). "Our data suggest that the kidneys of women with hypertensive pregnancies and endotheliosis have inappropriate intrarenal renin–angiotensin system activation, which may contribute toward the pathogenesis of hypertension and renal injury." (PMID 31237175, 2019). "The mechanism suggested was the renin-angiotensin system that involved in hypertension has activities in the central nervous system that may be related to migraine pathogenesis." (PMID 31309023, 2019). "AA patients with essential hypertension have repeatedly been shown to be more salt sensitive and more responsive to diuretics, with less activation of the circulatory renin-angiotensin-aldosterone system, and less sensitivity to ACE inhibition or angiotensin receptor blockade." (PMID 31532792, 2019). "Renin also plays a pivotal role in the development of hypertension." (PMID 31109113, 2019). "Increased activation of the renin-angiotensin system is a major stimulus for pathological cardiovascular remodeling, contributing to hypertension, endothelial dysfunction, cardiac hypertrophy, and heart failure, and previous work has shown an important role for Nox2 in amplifying these processes." (PMID 29688896, 2018). "Thus, the beneficial effects of resveratrol on DEX + TCDD-induced hypertension include reduction of oxidative stress, restoration of nitric oxide (NO) bioavailability, blockade of the renin–angiotensin system (RAS), and antagonizing AHR signaling pathway." (PMID 30127255, 2018). "Numerous pre-clinical and clinical renin–angiotensin system (RAS) in AD research may be able to explain the connection between hypertension and AD." (PMID 30301188, 2018). "Here we found that cold exposure leads to transient receptor potential melastatin 8 (TRPM8)-dependent, renin–angiotensin–aldosterone system (RAAS)-mediated hypertension, which subsequently induces small molecule and fluid extravasation, increases plasma Ig levels, and elicits immunosuppression." (PMID 29560109, 2018). "We expect that new medications, including those that affect the Renin–angiotensin–aldosterone system (e.g., angiotensin II receptor blocker neprilysin inhibitors) will be increasingly incorporated in the management of hypertension." (PMID 29670769, 2018).
Hypertension (continued). "The thesis carries the implication for intraoperative care that the subset of patients with “pure” high-renin hypertension will have marked arteriolar vasoconstriction and may be particularly sensitive to the vasodilating effects of anaesthetic agents." (PMID 29527133, 2018). "In addition, a renin-angiotensin system has been proposed in adipocytes, providing a link to hypertension." (PMID 30540802, 2018). "Diet might influence hypertension between men and women differently due to the renin-angiotensin system, sex hormones, or sex-specific genes, and increased inflammatory markers, which are related to the control of blood pressure." (PMID 29473892, 2018). "Patients with DM, hypertension and nephropathy are reported to have “low renin hypertension ”." (PMID 30332741, 2018). "Common mechanisms, such as upregulation of the renin-angiotensin-aldosterone system, oxidative stress, inflammation, and activation of the immune system likely contribute to the close relationship between diabetes and hypertension." (PMID 29459239, 2018). "Hypertension results from increased Na+ reabsorption at the distal nephron level, leading to volume expansion, which is also responsible for the observed biochemical phenotype of low renin and low serum aldosterone." (PMID 29534496, 2018). "A substantial proportion of patients with hypertension have a low or suppressed renin." (PMID 29439489, 2018). "Ang II, the main effector of the renin-angiotensin system, is a circulating peptide hormone and a potent vasoconstrictor that exerts key roles in the regulation of blood pressure and the development of hypertension." (PMID 29490666, 2018). "They suggested that renin may play a primary role along with other possible factors in the pathology of hypertension." (PMID 29849899, 2018). "Moreover, basic and clinical studies have demonstrated that the role of renin– angiotensin–aldosterone system (RAAS) in hypertension." (PMID 29751583, 2018). "Furthermore, increase in circulating and brain levels of the primary effector peptide of the renin–angiotensin–aldosterone system, angiotensin II (Ang-II), plays important roles in arterial hypertension, as well as the AD pathophysiology." (PMID 30301188, 2018). "LRH is characterized by the physiologic suppression of renin, often in the context of intravascular volume expansion; however, there are many potential pathophysiological events that can result in hypertension with a low-renin phenotype that will be discussed in this review." (PMID 29439489, 2018). "Moreover, treatment of hypertension often includes renin-angiotensin-aldosterone inhibitors (angiotensin-converting enzyme inhibitors and angiotensin receptor blockers) that lower hydrostatic pressure in glomeruli and thus normalize albuminuria." (PMID 30158836, 2018). "Delayed CoA repair may therefore lead to more abnormal development of the renin–angiotensin–aldosterone system, which may in turn lead to hypertension and concomitant increased LV afterload." (PMID 29209744, 2018). "Therefore, the absence of vitamin D receptor activation leads to tonic upregulation of the renin-angiotensin system, eventually leading to hypertension and left ventricular hypertrophy and increasing the likelihood of MetS." (PMID 32153897, 2018). "Our hypothesis was that cod meal prepared from residual materials and fillet would prevent or delay the development of high blood pressure in obese Zucker fa/fa rats, possibly through inhibition of the renin-angiotensin system." (PMID 30469459, 2018). "Aliskiren is a direct renin inhibitor that has been effective in anti-hypertension." (PMID 29184499, 2017). "Lipotoxicity per se may also facilitate the development of hypertension via activating renin-angiotensin-aldosterone system (RAAS) and amplifying vasoconstrictor response to angiotensin II." (PMID 28415694, 2017).
Hypertension (continued). "Brain renin-angiotensin system (RAS) could regulate oxidative stress in the paraventricular nucleus (PVN) in the development of hypertension." (PMID 28338001, 2017). "Although the application of RDN isnot clear because of its varying effectiveness, our data suggested that it may be anexcellent choice in obesity-related hypertension patients with high levels of NE andover-activation of the renin-angiotensin system." (PMID 28273198, 2017). "Increased activity of RhoA/ROCK pathway has been observed in experimental hypertension models and hypertensive patients, which appear to be the consequence of the up-regulation of renin-angiotensin-aldosterone system and the increased production of reactive oxygen species (ROS)." (PMID 29262624, 2017). "On the other hand, endothelial cell Nox2 activation may be more relevant to renin-angiotensin system–dependent hypertension." (PMID 28298457, 2017). "Our experimental findings suggest that several of these genes may be involved in the renin-angiotensin pathways in the kidney during hypertension." (PMID 28498854, 2017). "In patients with diabetes and hypertension, the calcium channel blocker amlodipine is superior to the diuretic hydrochlorothiazide when added to a renin-angiotensin system blocker for reduction of cardiovascular events in patients with diabetes requiring management of hypertension." (PMID 28725272, 2017). "It has been reported that resistin could induces hypertension in wild type (WT) mice by activating the renin-angiotensin system through up-regulation of Agt expression in the liver." (PMID 28525369, 2017). "We have previously examined the association between the HPA axis and the RAAS with regard to hypertension using PC analysis combining four hormones i.e. plasma renin activity (PRA), plasma aldosterone concentration, serum cortisol concentration and plasma ACTH concentration." (PMID 28900121, 2017). "Current proposed pathophysiologic mechanisms by which obesity may contribute to elevated BP and hypertension is reviewed, with focus on the role of the sympathetic nervous system and the renin–angiotensin–aldosterone system." (PMID 28993801, 2017). "In terms of renin-angiotensin-aldosterone system–dependent hypertension, Nox2 inhibition would be anticipated to be beneficial, and combined Nox1/Nox2 inhibitors could be of particular value given the effects of both isoforms to increase BP." (PMID 28298457, 2017). "On the other hand, suppressed RAS activity, as a consequence of low renin levels, may lead to the development of volume loading hypertension (low-renin hypertension)." (PMID 28446166, 2017). "Therefore, ACE and renin inhibitor makes a positive contribution to hypertension treatment and specific inhibitors are currently used in pharmaceuticals." (PMID 28282929, 2017). "Hyperuricemia may also induce proliferation of vascular smooth muscle cells and increase COX-2 expression and renal renin, leading to arteriopathy and hypertension–which may further aggravate kidney function." (PMID 28107415, 2017). "Diagnostics used to rule out causes or consequences of hypertension varied among the respondents; they included, in particular, the use of serum renin/aldosterone, urine sodium/potassium, and dimercaptosuccinic acid scan." (PMID 26940338, 2017). "Existed evidence demonstrated excess visceral adipose tissue could result in a feedback loop where obesity induced declines in kidney function lead to a further development of hypertension by activating the sympathetic nervous and renin-angiotensin systems." (PMID 27579531, 2017). "CsA and Tac might differ in their ability to cause vasoconstriction, activate the renin-angiotensin-aldosterone system (RAAS), or the sympathetic nervous system, all of which can contribute to the development of hypertension." (PMID 28430812, 2017).